INS (insulin)
Diseases named in the same sentence as INS in open-access papers (continued):
Sharing a sentence is not in itself a finding about the gene and the disease.
Insulin resistance (continued). "JNK was reported to drive insulin resistance via direct phosphorylation of insulin receptor substrate (IRS), a family of adaptor proteins that are essential for insulin effects." (PMID 31619254, 2019). "These patients may need insulin or secretagogues in the future when their glucose control worsens because their hyperglycemia is likely caused by absolute insulin deficiency rather than insulin resistance." (PMID 31485449, 2019). "Yet another meta-analysis showed that supplementation with probiotic reduced insulin resistance (HOMA-IR) and fasting serum insulin in women with gestational diabetes significantly, compared to healthy pregnant controls." (PMID 31828161, 2019). "The T2DM patients had higher fasting blood glucose (FBG), HbA1c, insulin, and alanine aminotransferase (ALT) levels, and homeostasis model of insulin resistance (HOMA-IR) values, than the control subjects." (PMID 31138957, 2019). "Homeostatic Model Assessment for Insulin Resistance (HOMA-IR; an index for assessment of insulin sensitivity) is positively correlated with FSP27 expression in BMI-matched obese individuals." (PMID 30871156, 2019). "Insulin resistance (IR) is a characteristic pathophysiological feature of T2DM, and is defined as a state in which an abnormally higher amount of insulin is required to elicit a quantitatively normal biological response." (PMID 31516543, 2019). "Here, for the first time, we provide evidence demonstrating that spexin inhibits hepatic gluconeogenesis to alleviate insulin resistance in high-fat-diet (HFD)-induced rats and insulin-resistant cells via the FoxO1/PGC-1α pathway." (PMID 31853220, 2019). "However, the subjects given CLA exhibited improved indices of glucose tolerance, such as reduced fasting insulin and homeostatic model assessment of insulin resistance (HOMA-IR), suggesting that CLA may improve obesity-associated insulin resistance in children." (PMID 30754681, 2019). "Although the temporal relationship between decreased GLUT4 expression and insulin resistance is unclear, a reduction in GLUT4 expression has been demonstrated in insulin resistant models based on genetically altered iPSCs." (PMID 30343468, 2019). "Previous study reported that IFG reflects defects in insulin secretion and IGT reflects insulin resistance." (PMID 30992067, 2019). "In a study conducted on high-fructose-fed rats, treatment with genistein improved insulin resistance by restoring homeostatic model assessment for insulin resistance (HOMA-IR) and quantitative insulin sensitivity check index (QUICKI) values." (PMID 31027340, 2019). "Induction of DM and increased insulin resistance in the tested animals was confirmed by an increased glucose level and HOMA-IR, as well as by a decreased insulin level in the DM group." (PMID 31308875, 2019). "Essentially, inflammatory signalling interferes with insulin signalling, with TNFα and several stress-related kinases (IκB kinase β (IKKβ), c-Jun N-terminal kinase (JNK)) being major mediators of insulin resistance." (PMID 31466350, 2019). "Conversely, insulin resistance induced by the HFD was efficiently attenuated by the HFDo/p, as reflected in significantly decreased plasma insulin levels than in HFD-fed mice." (PMID 30914769, 2019). "The mathematical model Homeostasis Model Assessment-Insulin Resistance (HOMA-IR) was used to calculate insulin resistance using insulin and fasting blood glucose measurements: HOMA‐IR = [(fasting insulin (μU/mL) × fasting blood glucose [mmol/L])/22.5]." (PMID 31933541, 2019). "Meanwhile, a significant decreasing trend was found regarding the percentage of male participants; AHI; BMI; fasting serum concentrations of glucose, insulin, and TG; HOMA-IR; and the percentage of participants with insulin resistance." (PMID 31089476, 2019). "AAV8-Arg2 mice exhibited lower serum insulin and glucose concentrations in both NCD-fed and HFrD-fed group which resulted in lower HOMA of insulin resistance (HOMA-IR)." (PMID 30962478, 2019).
Insulin resistance (continued). "Insulin resistance and compensatory hyperinsulinemia are present in women with PCOS and insulin sensitizing drugs such as inositols are effective in improving PCOS symptoms." (PMID 31877155, 2019). "In the present study, we investigated the dynamic changes of insulin sensitivity and the PI3K/Akt related signaling activities in skeletal muscle tissues as well as the correlation of catch-up growth with insulin resistance in rat IUGR offsprings." (PMID 31071176, 2019). "Hepatic insulin resistance is an important pathophysiological feature of obesity, and PI3K/Akt2 are the main components of the insulin signalling pathway." (PMID 31270932, 2019). "Greater alteration of insulin resistance clinical profiles, such as BMI, WC, waist/hip ratio, HOMA IR, and insulin, was observed in the group of patients with AO-GHD compared to the CO-GHD group." (PMID 31275240, 2019). "In company with the improvement in insulin signaling pathway in palmitate-treated hepatocytes, SFC treatment improved HFD-induced hepatic insulin resistance." (PMID 31780766, 2019). "Insulin resistance occurs before the progression of T2DM, with several metabolic markers (such as fasting glucose, glycosylated hemoglobin, and insulin) correlating with the presence of Lactobacillus and Clostridium." (PMID 31835423, 2019). "After 6 weeks, Alanine aminotransferase (ALT), glucose, insulin, HOMA IR (Homeostatic Model Assessment for Insulin Resistance), FFA (free fatty acids), Tumor necrosis factor alpha (TNF α), IL6, IL1B levels were measured in blood." (PMID 31496048, 2019). "As expected, the clinical factors defining insulin resistance by HOMA-IR (i.e., fasting glucose and insulin) were significantly higher among IR individuals compared to IS individuals (P < 0.05)." (PMID 31253200, 2019). "Insulin resistance can be clinically assessed using, e.g., the homeostatic model assessment for insulin resistance (HOMA-IR) from fasting insulin and glucose levels." (PMID 31275108, 2019). "Retinol-binding protein 4 (RBP4), a cytokine secreted by adipocytes, led to insulin resistance and negatively correlated with the expression of GLUT-4 in insulin-resistant states." (PMID 31396083, 2019). "Another report has shown that reduction of GM3 in the liver via hepatic NEU3 overexpression improved insulin sensitivity and glucose tolerance in mice, indicating that GM3 contributes to insulin resistance in the liver." (PMID 31013778, 2019). "In our study, these three indices were all moderately correlated with an index of insulin resistance (HOMA-IR) and showed a smaller correlation with insulin secretion (HOMA-B)." (PMID 31183505, 2019). "Therefore, BMLE offers superior control of hyperglycemia and improvements in insulin resistance and insulin sensitivity than MLE, which suggests that bioconversion may be an important process for maximizing the pharmacological efficacy of natural product extracts." (PMID 30841887, 2019). "The elevated levels of luteinizing hormone (LH) and insulin resistance are typical symptoms exhibited by women with anovulation and PCOS; moreover, the dysfunction of LH and insulin interactions can affect the terminal differentiation of GCs." (PMID 30937532, 2019). "In summary, to the best of our knowledge, the results of the present study shows, for the first time, that spexin improves insulin resistance in HFD-induced rats and insulin resistant cells." (PMID 31853220, 2019). "Then, we calculated the homeostasis model assessment of insulin resistance (HOMA-IR) index and the quantitative insulin sensitivity check index (QUICKI)." (PMID 31096578, 2019). "Coexistence of insulin resistance is found in 50-80% of women with PCOS, leadingto decreased insulin sensitivity and hyperglycemia and hyperinsulinemia,followed by hyperandrogenism and chronic anovulation." (PMID 30875185, 2019).
Insulin resistance (continued). "Recent studies in PAH patients reported a specific pattern of metabolic alterations, including insulin resistance defined as elevated triglyceride to HDL cholesterol ratio, glucose intolerance, and a blunted insulin response to an oral glucose load." (PMID 31323735, 2019). "HOMA is a method used to quantify insulin resistance and beta cell function, computed as the product of fasting plasma glucose (FPG, mmol/L) and fasting serum insulin (mU/L) divided by 22.5." (PMID 31443279, 2019). "Furthermore, lipid infusion induced a 30% decrease in insulin sensitivity in endurance athletes compared to a 70% decrease in sedentary controls suggesting that higher mitochondrial oxidative capacity, typical of endurance athletes, partially protects against lipid-induced insulin resistance." (PMID 31130874, 2019). "In one study, it was reported that CTRP5-deficient mice showed reduced hepatic steatosis and improvement of insulin resistance, and treatment with recombinant CTRP5 inhibited insulin-stimulated Akt phosphorylation." (PMID 29964236, 2019). "In HFD mice, both the serum insulin concentration and HOMA-IR value were increased significantly, which indicating that there was an insulin resistance in NAFLD mice (P < 0.001)." (PMID 31803542, 2019). "With regard to the relationships among thyroid hormones, glucose metabolism and insulin resistance, FT4 was significantly inversely correlated with insulin and HOMA-IR." (PMID 31664103, 2019). "Intriguingly though, a second HFD challenge in adulthood resulted in substantially increased insulin levels and the HOMA-IR indicator of insulin resistance in early-HFD mice and a strong trend of higher levels in early-R-HFD compared to early-CD mice." (PMID 31003943, 2019). "Moreover, brain insulin resistance typically results in increased hypothermia, augmented hepatic glucose output and impaired response to hypoglycemia, all characteristics mirrored in the Tau KO animals, clearly suggesting the presence of reduced brain insulin signaling in these animals." (PMID 30804755, 2019). "Homeostatic Model assessment for insulin resistance (HOMA-IR) and insulin were higher in obese and overweight subjects compared to NW (p-value < 0.01 and 0.05, respectively, in both comparisons)." (PMID 31212599, 2019). "Our previous report showed that Hibiscus sabdariffa polyphenols (HPE) improved insulin sensitivity by attenuating DPP-4 and the downstream signals in the palmitate-induced model displaying insulin resistance." (PMID 31237881, 2019). "A previous study has indicated that insulin resistance is usually presented in individuals with NAFLD, in which insulin cannot inhibit the lipolysis rate of white adipose tissue, allowing large amounts of free fatty acids entry into the liver." (PMID 30060615, 2018). "Consequently, the fact that most T2D SNPs associate with beta cell dysfunction and thus insulin secretion, while dietary factors may more likely associate with insulin resistance, could partly explain the lack of interaction between the GRS and the DRS." (PMID 29796113, 2018). "Levels of fasting blood glucose, serum insulin, C-peptide or leptin, and HOMA-IR index representing insulin resistance that were increased in HFD-fed mice were significantly lowered by MSL-7 administration for 8 weeks." (PMID 29650965, 2018). "Obese subjects had high values of basal glycemia, basal insulin, and HOMA-IR, indicating insulin resistance in this group." (PMID 29896216, 2018). "In acromegaly, HSI is mainly related with insulin resistance and the reduction of GH and IGF-1 levels, and above all the improvement in insulin sensitivity leads to an improvement of this surrogate index of hepatic steatosis." (PMID 30662461, 2018). "However, insulin resistance in obese participants during a 12 h fast does not appear to involve oxidation of ketone bodies, but can instead be caused by impairment in insulin signaling or other unknown factors." (PMID 30183740, 2018).
Insulin resistance (continued). "Several lines of evidence indicate that insulin resistance alone does not, usually, cause type 2 diabetes; most insulin-resistant individuals have various compensatory mechanisms to meet the body’s requirement of insulin, which include an increase in both β cell proliferation and insulin secretion." (PMID 29770126, 2018). "In our study, sinapic acid reduced insulin resistance determined by the calculated HOMA-IR index, which is widely used to assess insulin sensitivity in humans and experimental animals." (PMID 29967666, 2018). "In our study, FBG, insulin concentration, IR index, TG, TC, and FFA increased dramatically in the model group, indicating that glucolipotoxicity and insulin resistance occurred in T2DM." (PMID 30356368, 2018). "To investigate the effects of METRNL on palmitate-induced insulin resistance, we examined the effect of METRNL on insulin-stimulated IRS-1 and Akt phosphorylation and glucose uptake." (PMID 30213948, 2018). "Fasting insulin resistance was assessed by HOMA-IR, and insulin sensitivity during the OGTT was assessed by the Matsuda Index." (PMID 30042734, 2018). "Compared with the control group, HFD group exhibits increased levels of FPG, FINS, and homeostatic model assessment of insulin resistance (HOMA-IR) and decreased level of ADP and insulin sensitivity index (ISI)." (PMID 30524482, 2018). "We further explored the status of insulin resistance in the liver of HFD-fed floxed and AKO mice by detecting the endogenous activity of insulin signaling." (PMID 29515462, 2018). "To assess the molecular basis of insulin resistance observed in HFD-ΔdblGATA mice, we investigated insulin receptor signalling after infusion of insulin through the portal vein." (PMID 29967467, 2018). "In this article, we will review the clinical and experimental evidences linking insulin resistance, T2DM and neurodegeneration, with the objective to specifically focus on insulin signalling-related mechanisms." (PMID 30355995, 2018). "Insulin resistance that impairs the expression and translocation of GLUT4, and disturbs insulin signaling pathway in cardiomyocytes, was observed in various animal T2D models." (PMID 29959408, 2018). "Homeostatic Model Assessment of Insulin Resistance (HOMA-IR), derived from an equation with fasting glucose and insulin, is an important technique for the diagnosis and surveillance of insulin resistance, being a marker of type 2 diabetes mellitus." (PMID 30513771, 2018). "The key role is played by the insulin-stimulated PI3K/Akt/eNOS signaling and pathway, that are impaired in insulin resistance, so in prediabetes." (PMID 29052766, 2018). "The results of this study suggest a new insight into the interrelationship among plasma BCAAs, adipokines, and insulin resistance; previous reports have focused mainly on the adipokine—insulin resistance and BCAA—insulin resistance relationships." (PMID 29348480, 2018). "Normally, insulin, through PI3K activation, promotes the degradation of apoB, but under insulin resistance this degradation is impaired." (PMID 30170598, 2018). "Applying BAKE to genomic expression data collected from mouse (Mus musculus) adipocytes during insulin resistance progression, we uncovered the transcription factor Krueppel-like Factor 4 (KLF4) as a regulator of early insulin signaling." (PMID 30240435, 2018). "ROS have been reported to play a major role in FFA-induced insulin resistance by phosphorylating insulin receptor substrate-1 (IRS-1) in serine residue and by inhibiting the downstream insulin signaling." (PMID 29675131, 2018). "While young mice developed only slightly impaired insulin tolerance under the HFD feeding, compared to ND, insulin resistance worsened in the aged mice." (PMID 29426925, 2018). "A fasting blood sample was used for measurement of insulin, glucose (from which homeostasis model assessment [HOMA]‐insulin resistance [IR] was derived), glycated hemoglobin (HbA1c), urate, C‐reactive protein (CRP), and lipids." (PMID 29411507, 2018).
Insulin resistance (continued). "The homeostasis model assessment-estimated insulin resistance (HOMA-IR) index and the quantitative insulin-sensitivity check index (QUICKI) will be calculated." (PMID 29343256, 2018). "Hyperinsulinemia was also observed (216%), in concordance with insulin resistance by HOMA (157%) and IDA-IR (2450%), both greater than the control group, while hepatic insulin sensitivity fell (73%)." (PMID 30201894, 2018). "Notably, while insulin and insulin-sensitizing drugs have beneficial effect in dementia, it has also been proposed that persistent activation of insulin receptors could be the trigger for brain insulin resistance." (PMID 30686981, 2018). "Our findings further support the critical need for functional actin remodeling for skeletal muscle insulin action and the potential role for effectors of Rac1, such as PAK, in the development of insulin resistance." (PMID 30592185, 2018). "For insulin sensitivity, HOMA-IR decreased in the NGT and IGT groups and remained unaltered in the DM group, while ISOGTT, another major parameter reflecting insulin resistance, improved in all groups." (PMID 29853879, 2018). "Additional studies are needed to further elucidate the potential role of mTOR/SGK1 and INS docking proteins INS receptor substrates 1 and 2 as mediators of the efficacy of SIT on insulin resistance." (PMID 30116740, 2018). "An increase in insulin resistance was shown in our comparison of women with GWG above and below the median, and insulin secretion was also greater, suggesting a compensatory increase." (PMID 30360536, 2018). "T2DM induction increased insulin resistance (FIRI index) and decreased insulin sensitivity (QUICKI index) when compared to the control group (p < 0.05)." (PMID 30186630, 2018). "Levels of glucose and insulin levels and HOMA-IR index under fasting condition were measured to detect insulin resistance." (PMID 30429827, 2018). "The Homeostatic Model for Assessment of Insulin Resistance (HOMA-IR) is a validated algorithm that uses the product of fasting blood glucose and insulin to assess the extent to which the glucose-insulin feedback loop is disrupted." (PMID 30149556, 2018). "We evaluated the improvement of insulin resistance and studied the effect of Modified Sanzi Yangqin Decoction on IRS-1, p-IRS-1(Tyr895), and PTP1B, key molecules involved in the insulin signal transduction pathway." (PMID 29721029, 2018). "Intraperitoneal glucose tolerance test and insulin tolerance test showed HFD group mice had hyperglycemia and insulin resistance." (PMID 29530061, 2018). "We also detected decreased serum triglycerides (p = 0.036), homeostatic model assessment insulin resistance (HOMA-IR (p = 0.041) and insulin content (p = 0.34), and improvement of fatty liver status according to the Hamaguchi score (p = 0.009)." (PMID 30453660, 2018). "In insulin-sensitive tissues such as liver, skeletal muscle and adipose tissue from the guinea pig, TCDD induced insulin resistance, possibly by downregulation of glucose transporters." (PMID 29744538, 2018). "This appears to dissociate lipid accumulation and PKCε activation from the generation of liver insulin resistance, and similar discrepancies regarding hepatic DAG levels and insulin action have been reported." (PMID 29439143, 2018). "Insulin-mediated AKT was decreased in HFD-induced obesity, and AKT2−/− mice developed peripheral insulin resistance and showed hepatic glucose production." (PMID 30360437, 2018). "Activation of HIF-1α in adipose tissue leads to insulin resistance, while silence of HIF-1α in adipocytes protects mice from glucose tolerance by enhancing insulin secretion." (PMID 30622603, 2018). "Thus, increasing both glucagon-like peptide 1 secretion and adiponectin production by omega-3 fatty acids could improve both insulin secretion and sensitivity resulting in improved recovery from insulin resistance and dyslipidemia, thus attenuating metabolic syndrome." (PMID 29794984, 2018).